TFPI2 (tissue factor pathway inhibitor 2)
Diseases named in the same sentence as TFPI2 in open-access papers (continued):
Sharing a sentence is not in itself a finding about the gene and the disease.
tumor (continued). "Additional studies have shown that TFPI-2 inhibits tumor-related angiogenesis and some members of the extracellular matrix (ECM) therefore implicates tumor invasion and progression." (PMID 21062455, 2010). "Epigenetic inactivation of TFPI-2 by promoter hypermethylation is a frequent and tumor specific event in NPC." (PMID 21062455, 2010). "Recently, TFPI-2 was suggested to be a tumor suppressor gene involved in tumorigenesis and metastasis in some cancers." (PMID 21062455, 2010). "Studies have demonstrated that TFPI-2 is a strong serine protease inhibitor with broad inhibitory spectra, whose expression can decrease the invasion capacity of various tumor cells." (PMID 19936309, 2009). "Its secretion in the extracellular matrix makes TFPI-2 a potential inhibitor of tumor cell invasion." (PMID 19936309, 2009). "TFPI-2, a 32 kDa serine proteinase inhibitor, is known to play a regulatory role in several processes relevant to the pathogenesis of tumor invasion." (PMID 19936309, 2009). "The existence of an aberrantly-spliced variant of TFPI-2 that is untranslated, and appears to be highly upregulated in tumor cells, suggests an additional, novel mechanism for further downregulation of TFPI-2 expression in tumor cells." (PMID 17352822, 2007). "In view of its apparent role in cancer progression, we initiated a study to quantify TFPI-2 transcript levels in total RNA samples from selected normal human tissue, as well as their corresponding tumor tissue." (PMID 17352822, 2007). "Accordingly, the TFPI-2 gene is becoming increasingly recognized as a tumor suppressor gene, since its down-regulation in several types of cancers allow for enhanced tumor growth and metastasis." (PMID 17352822, 2007). "Hypermethylation of the TFPI-2 gene promoter has been described recently as a possible mechanism for gene silencing in a limited number of tumor cell lines." (PMID 17352822, 2007). "By this procedure, normal cells synthesize ~10-fold more wild-type TFPI-2 transcripts than tumor cells, whereas tumor cells synthesized 4–50 times more asTFPI-2 than normal cells." (PMID 17352822, 2007). "The results obtained in this study strongly suggest an additional mechanism in tumor cells to down regulate TFPI-2 expression by aberrant splicing." (PMID 17352822, 2007). "In preliminary studies designed to assess the levels of TFPI-2 transcripts in various normal and tumor tissues, co-amplification of a lower molecular weight cDNA was observed following RT-PCR of total RNA." (PMID 17352822, 2007). "In experiments designed to quantify TFPI-2 transcripts in human normal and corresponding tumor tissues using RT-PCR, we observed two TFPI-2 amplicons, using exon II (sense) and exon V (anti-sense) primers." (PMID 17352822, 2007). "An apparent variation in the transcripts levels of TFPI-2 and asTFPI-2 from primary cells and tumor cells was observed by semi-quantitative RT-PCR, and subsequently validated by quantitative real-time RT-PCR analysis." (PMID 17352822, 2007). "In this regard, overexpression of TFPI-2 in several tumor cells was shown to inhibit their growth, invasiveness, angiogenic potential and metastatic potential." (PMID 17352822, 2007). "Previous studies have shown that the expression of tissue factor pathway inhibitor-2 (TFPI-2), a matrix-associated Kunitz-type serine proteinase inhibitor, is markedly down-regulated in several tumor cells through hypermethylation of the TFPI-2 gene promoter." (PMID 17352822, 2007). "The number of TFPI-2 transcripts within the tumour was higher than 2500 for 107 18S RNA copies in 11 cases (‘High TFPI-2’ group), while it was lower than 100 in the 11 others (‘Low TFPI-2’ group)." (PMID 15685245, 2005). "The amount of TFPI-2 mRNA within the tumour was therefore considered to be significantly different to the amount in the noncancerous lung when the NTFPI-2 value was either >4 (i.e. increased) or <0.25 (i.e. decreased)." (PMID 15685245, 2005).
tumor (continued). "Immunostaining for TFPI-2 protein was studied in lung samples of two groups of patients defined according to TFPI-2 gene expression within the tumour." (PMID 15685245, 2005). "Dot blot analysis performed on selected samples also confirmed that TFPI-2 protein levels were lower in tumours in which few transcripts of TFPI-2 gene were measured." (PMID 15685245, 2005). "In a few tumours, TFPI-2 was almost undetectable in cancerous cells, contributing to the lower protein expression measured for samples expressing not many TFPI-2 mRNA copies." (PMID 15685245, 2005). "TFPI-2 is a 32 kDa Kunitz-type serine proteinase inhibitor also previously shown to reduce tumour invasion." (PMID 15685245, 2005). "Tumour TFPI-2 mRNA levels appeared well correlated with protein expression evaluated by immunohistochemistry and were 4–120 times lower compared to those of nonaffected lung tissue in 22 cases (37%)." (PMID 15685245, 2005). "Within tumours, both stroma cells and cancerous cells were shown to express varying amounts of TFPI-2 protein, and a good correlation between the staining score and mRNA levels measured by real-time PCR was found." (PMID 15685245, 2005). "Within the TME, TFPI2 may paradoxically facilitate tumor progression, inducing M2 macrophage polarization and stabilizing VEGF-mediated angiogenesis." (PMID 40361374, 2025). "We identified several spatial biomarkers linked to non-recurrence, including elevated NKG7 expression in CD45+ immune cell regions (p = 0.0011) and higher TFPI2 and PIGR expression in tumor areas (p = 2.09 × 10−6), both associated with improved progression-free survival." (PMID 40422184, 2025). "Though often considered a tumor suppressor, TFPI2 can promote tumor progression in certain cancers." (PMID 40361374, 2025). "Additionally, we established orthotopic and subcutaneous xenograft tumor models using TFPI2-overexpressing HCC cells." (PMID 40765823, 2025). "The tumor-promoting effects of TFPI2 may be particularly pronounced in cancer types that exhibit a strong dependence on the tumor microenvironment." (PMID 40361374, 2025). "Additionally, TFPI-2 blocked PSAP-induced enhancement of matrix metalloproteinase-2 (MMP-2) activity, which is closely linked to tumor cell invasive/migratory capabilities." (PMID 40801564, 2025). "On the one hand, this may be related to gene silencing via promoter hypermethylation, while on the other, aberrantly spliced TFPI-2 transcript has also been observed in tumor cells." (PMID 39153052, 2024). "TFPI2 also acts as a tumor suppressor gene to induce tumor cell apoptosis." (PMID 39617791, 2024). "All in all, focusing on the TF pathway, the deregulation of TF and TFPI2, both targeted by miR-20a-5p, might contribute to the tumour coagulome and OC progression." (PMID 39199316, 2024). "As an inhibitor of MMPs, TFPI-2 restricts matrix degradation promoted by invading tumor cells." (PMID 39153052, 2024). "A growing body of evidence indicates that TFPI-2 is a relevant tumor suppressor which is related to its regulation of extracellular matrix (ECM) and fundamental to normal development as well as tumor invasion/metastasis, atherosclerosis and chronic inflammation." (PMID 39153052, 2024). "The negative associations between TFPI-2 levels and tumor malignancy and progression have been reported for decades." (PMID 39153052, 2024). "CD24 could inhibit the tissue factor pathway inhibitor-2 (TFPI-2) by regulating the Src related pathway, and then promote the metastasis of tumor cells." (PMID 37359556, 2023). "TFPI2 belongs to the Kunitz-type serine proteinase inhibitor family and functions as a tumor suppressor gene in multiple cancer types due to its ability to inhibit tumor cell growth, metastasis, and invasion." (PMID 37559681, 2023). "Some studies have reported that TFPI2 may inhibit tumour metastasis by inhibiting tumour angiogenesis, but there is no convincing clinical evidence to support it." (PMID 35501390, 2022).
tumor (continued). "Overexpression of TFPI2 prevented tumour invasion and metastasis in pancreatic cancer." (PMID 35039572, 2022). "Since it has been reported that TFPI2 may inhibit tumour metastasis by inhibiting the angiogenesis of tumour cells, we measured CD34 levels as well." (PMID 35501390, 2022). "TFPI2 is a Kunitz-type serine proteinase inhibitor that has been identified as a tumour suppressor." (PMID 35501390, 2022). "MBD3 plays a tumour-promoting role in HCC through epigenetic regulation of TFPI2 transcription." (PMID 35501390, 2022). "Also, SsGESA and ESIMATE were conducted to examine the relationship between the expression of SERPINF1 and TFPI2 with tumor microenvironment in GC." (PMID 36505458, 2022). "FA-MNP/CDDP/TFPI-2 showed good gene delivery ability in vitro and could specifically target FA-positive cells and tumor tissue, thus effectively treating FR-positive NPC." (PMID 33967612, 2021). "However, subgroup analyses in accordance with tumor stages revealed that TFPI2 levels were higher in stage II–IV CCC patients (median 499.9 pg/mL) than other groups." (PMID 34009487, 2021). "The expression of TFPI2 was negatively correlated with tumor invasion and proliferation." (PMID 33815468, 2021). "Based on these results, TFPI2 has been regarded as a tumor suppressor gene." (PMID 34249699, 2021). "Tumor‐related functions of TFPI2 have been reported in other malignancies." (PMID 32406600, 2020). "Reduction of TFPI-2 protein levels in tumor-associated fibroblasts, although the gene was not methylated, suggested alternative regulatory mechanisms of gene expression, such as inhibition by microRNAs." (PMID 32559232, 2020). "Several recent studies verified the tumor suppressor function of TFPI-2." (PMID 32559232, 2020). "These indicate that MM can be stratified into at least two different epigenetic subgroups, that the MM subgroup with higher DNA methylation shows a more progressive phenotype, and that methylation of TFPI2 may contribute to the tumor progression of MM." (PMID 32406600, 2020). "In all, depletion of AGAP2-AS1 impaired tumor xenograft possibly by modulating TFPI2." (PMID 31186379, 2019). "Additionally, knockdown of AGAP2-AS1 triggered a reduction of AGAP2-AS1 expression, while an increase of TFPI2 protein level in excised tumor masses." (PMID 31186379, 2019). "Our study thus highlights the finding that TFPI2 is hypermethylated in most OSCC tumor samples we tested in this study, suggesting that TFPI2 may be a useful biomarker for screening OSCC patients." (PMID 31405379, 2019). "Finally, depletion of AGAP2-AS1 impaired GBM tumor growth in vivo possibly through increasing TFPI2 expression." (PMID 31186379, 2019). "Furthermore, the tumor-suppressive effects mediated by AGAP2-AS1 knockdown were greatly reversed following down-regulation of TFPI2." (PMID 31186379, 2019). "Finally, the protein expression of TFPI-2 was measured in primary GB, relapsed GB, and non-tumor primary GB tissues." (PMID 30442884, 2018). "Furthermore, the expression of TFPI2 is frequently silenced by promoter methylation in many tumor tissues including HCC." (PMID 29757260, 2018). "Tissue factor pathway inhibitor 2 (TFPI2) gene could protect the extracellular matrix of cancer cells from degradation and tumor invasion." (PMID 29137404, 2017). "TFPI-2 is a member of the Kunitz-type serine proteinase inhibitor family and has been shown to protect the extracellular matrix from degradation, thereby inhibiting tumor cell invasion and metastasis." (PMID 29051606, 2017). "Showing that angiogenic factors stimulate trypsinogen 4 expression, which hydrolyses TFPI-2 favoring a pro-migratory situation, our study suggests a new pathway linking tumor microenvironment signals to endothelial cell migration, which is essential for angiogenesis and blood vessel remodeling." (PMID 26318044, 2015). "Silencing tumor-EC for trypsinogen 4 accumulated TFPI2 in the matrix." (PMID 26318044, 2015).
tumor (continued). "In contrast, and as expected for a role in tumor suppression, TFPI2 expression was decreased." (PMID 26501324, 2015). "Next we determined whether trypsinogen 4 could cleave TFPI-2 in a complex biological sample, such as the matrix of tumor-EC." (PMID 26318044, 2015). "TFPI2 appears to be a perfect example of how an endogenous thrombin inhibitor can serve to normally keep the coagulation cascade in check, ultimately fulfilling a tumor suppressor role." (PMID 24489651, 2014). "The level of TFPI-2 expression was observed to be significantly higher in gastric normal tissue than in peritumoral tissue, and was significantly higher in peritumoral tissue than in tumor tissue (P<0.01)." (PMID 24396436, 2014). "In addition, the TFPI-2 methylation level in tumor tissues was higher at the P4 stage than at earlier stages (P1 and P2)." (PMID 25179542, 2014). "Collagen zymography was performed on conditioned medium from the transduced OC2 cells in order to examine whether tumor-secreted proteases were targeted by TFPI-2 inhibition." (PMID 25179542, 2014). "We investigated whether TFPI-2 plays a role as a tumor suppressor by establishing TFPI-2-overexpressing OSCC cells and subjecting them to in vitro cellular proliferation, migration, and invasion assays, as well as an in vivo metastasis assay." (PMID 25179542, 2014). "Methylation-mediated inactivation is reversible, up-regulating TFPI-2 by demethylating agent may reverse the malignant phenotype of tumor cells." (PMID 21062455, 2010). "Recent studies also suggest TFPI-2 may function in the maintenance of the stability of the tumor environment and inhibit the growth of neoplasms, thus act as a candidate TSG with important roles in carcinogenesis and metastasis in human cancers." (PMID 21062455, 2010). "Human TFPI-2, an ECM-associated Kunitz-type serine proteinase inhibitor, is thought to play a significant role in the regulation of plasmin-mediated ECM degradation during tumor cell invasion and metastasis, wound healing, and angiogenesis." (PMID 17352822, 2007). "Our laboratory, as well as others, have previously reported that overexpression of candidate tumor suppressor TFPI-2 gene in several highly metastatic tumor cells markedly inhibits their growth and metastasis in-vivo by regulating pericellular extracellular matrix (ECM) remodeling and angiogenesis." (PMID 17352822, 2007). "Moreover, the proportion of asTFPI-2 to that of wild-type TFPI-2 was 7–12-fold higher in tumor cells, while in normal cells, the asTFPI-2 transcript was very low to negligible." (PMID 17352822, 2007). "In order to assess the relative levels of the TFPI-2 and asTFPI-2 transcripts, we used semi-quantitative RT-PCR and quantitative real-time PCR and observed a dramatic difference in the levels of these two transcripts in normal cells and tumor cells." (PMID 17352822, 2007). "Tissue factor pathway inhibitor-2 (TFPI-2) is a matrix-associated Kunitz inhibitor that inhibits plasmin and trypsin-mediated activation of zymogen matrix metalloproteinases involved in tumor progression, invasion and metastasis." (PMID 18053161, 2007). "Several tumor cell lines were less invasive when they were stably transfected with TFPI-2." (PMID 18053161, 2007). "In addition, the staining scores obtained for the 11 tumours expressing limited amounts of TFPI-2 mRNA were also significantly lower than those of the ‘High TFPI-2’ group." (PMID 15685245, 2005). "Reduced synthesis in NSCLC of TFPI-2, a potent inhibitor of plasmin, might therefore contribute to tumour invasiveness and metastases in vivo." (PMID 15685245, 2005). "Human TFPI-2 could also regulate tumour angiogenesis by reducing synthesis of the VEGF receptor and affect the expression of several genes involved in oncogenesis, invasion and apoptosis." (PMID 15685245, 2005). "Consequently, TFPI2 is widely regarded as a tumor suppressor." (PMID 40361374, 2025).
tumor (continued). "Furthermore, numerous studies have reported that TFPI2 downregulation in cancer cells facilitates tumor progression by promoting extracellular matrix degradation and remodeling, underscoring its role as a tumor suppressor gene." (PMID 40361374, 2025). "However, TFPI2 paradoxically facilitates tumor progression in certain malignancies." (PMID 40361374, 2025). "TFPI, as the precursor mRNA of hsa_circ_0057335, has been proved to be closely related to the increased expression of CD33 in CHOL and the decreased expression of TFPI‐2 may inhibit cell migration and tumor invasion, playing an essential role in the carcinogenesis and progression of CHOL." (PMID 40304434, 2025). "TFPI-2 is thought to interact with actinin-4 and myosin-9 in the cytoplasm, with AP-2α in the nucleus and with the ERK-signaling pathway, affecting nuclear localization of pERK1/2, which, as a result, causes inhibition of tumor cell motility, proliferation and invasion." (PMID 39153052, 2024). "Additionally, TFPI-2 has been implicated in maintaining the integrity of the structure of the extracellular matrix (ECM) structure, and inhibiting the invasion and metastasis of tumor cells." (PMID 33967612, 2021). "Moreover, the upregulation of P14ARF could generate activation or interaction with other factors such as Sp1, c-Jun, AP-1, and JNK that cooperate to prevent tumor-induced microthrombosis through activation of the anticoagulant factor TFPI-2." (PMID 32982771, 2020). "TFPI2 could protect the extracellular matrix of cancer cells from degradation and tumor invasion." (PMID 29137404, 2017). "Here we used EC isolated from cancer specimens (tumor-EC) and show thattrypsinogen 4 is required for the migration of tumor-EC promoted by thetumor microenvironment, and exerts its pro-angiogenic action through the inhibition of the tissue factor pathway inhibitor-2 (TFPI-2)." (PMID 26318044, 2015). "Moreover, TFPI-2 hypermethylation could be used to discriminate the early-stage tumor tissues from the normal ones." (PMID 25179542, 2014). "TFPI-2 hypermethylation could be used to discriminate tumor tissues from the normal ones." (PMID 25179542, 2014). "TFPI-2 is frequently silenced in cancer and has been proposed to act as an anti-metastasis gene as its down-regulation may contribute to pathological processes such as tumour invasion and metastasis." (PMID 23703216, 2013). "TFPI-2 expression in tumor tissue could inhibit invasion, tumor growth, and metastasis." (PMID 21941675, 2011). "Thus, hypermethylation of TFPI-2 is a frequent and highly tumor-specific event in NPC." (PMID 21062455, 2010). "TFPI-2 might be considering as a putative tumor suppressor gene in NPC." (PMID 21062455, 2010). "Additionally, the expression of tissue factor pathway inhibitor 2 (TFPI2), a gene which is a negative inhibitor of aberrant angiogenesis associated with tumor development was increased 5-fold by K13." (PMID 19660139, 2009). "Whether or not these mechanisms are also regulated within the lung by TFPI-2 has to be evaluated, but our findings strongly suggest that low expression of the TFPI-2 gene by tumour or stroma cells could also favour the development of NSCLC and metastases in vivo." (PMID 15685245, 2005). "The TFPI-2 gene might therefore be a candidate tumour suppressor gene." (PMID 15685245, 2005). "Tissue factor pathway inhibitor 2 (TFPI2), a serine protease inhibitor, plays a multifaceted role in tumor metastasis." (PMID 42216563, 2026). "Indeed, TFPI2 may promote tumor growth by driving macrophage polarization." (PMID 40361374, 2025). "We identified the expression of NKG7 by immune cells, as well as TFPI2 and PIGR in the tumor area, as potential biomarkers that predict recurrence and survival of patients with HGSC." (PMID 40422184, 2025). "In HCC, all-trans retinoic acid (ATRA) enhances TFPI2 via retinoic acid receptor alpha (RARα), modulated by MAF bZIP transcription factor B (MAFB, activator) and MAFF (repressor), influencing tumor invasion." (PMID 40361374, 2025).